RSPO1 (R-spondin 1)
Diseases named in the same sentence as RSPO1 in open-access papers (continued):
Sharing a sentence is not in itself a finding about the gene and the disease.
diabetes (3 papers, 2015 to 2025). "Altogether, our data clearly demonstrate a potent ability of RSPO1 in inducing human functional β cell neogenesis, thereby opening new avenues in the context of diabetes research." (PMID 40339569, 2025). "Such activities of RSPO1 to promote β cell neogenesis could therefore represent an unprecedented hope in the continued search for diabetes alternative therapies." (PMID 40339569, 2025). "To further define the potential of RSPO1 in an autoimmune T1D-like context, we selected non-obese diabetic (NOD) mice, which spontaneously develop diabetes as result of leukocytic infiltration within the pancreatic islets." (PMID 40339569, 2025).
squamous cell carcinoma of the skin (3 papers, 2013 to 2018). "Loss of either RSPO1 or LGR4 increases the risk of developing squamous cell carcinoma of the skin, indicating that RSPO1-LGR4 signaling plays a vital role in the negative regulation of cell proliferation in the skin." (PMID 24205130, 2013). "The strong expression of LGR4 in basal and granular cells is consistent with the findings that LGR4 plays a critical role in these cells as loss of LGR4 or RSPO1 led to increased risk of squamous cell carcinoma of the skin in human." (PMID 24205130, 2013).
acute lymphocytic leukemia (2 papers, 2022 to 2026). "There are several oncogenic proteins such as EPHA3 and RSPO1, RSPO2, and RSPO3, which are overexpressed in lung adenocarcinomas and lymphoblastic leukemia and define the patient’s survival rates." (PMID 36139498, 2022).
adenovirus infection (2 papers, 2015 to 2017). "The adenovirus infection rate after 48 h in tumor tissue was determined, and the level of Rspo1 mRNA in the tumor was determined 48 h after adenovirus infection." (PMID 25865226, 2015).
atherosclerosis (2 papers, 2023 to 2025). A disease characterized by the build-up of fatty material and calcium deposition in the arterial wall resulting in partial or complete occlusion of the arterial lumen. "However, the specific role of RSPO1 in endothelial inflammation remains understudied, given the pleiotropic role of Wnt/β-catenin signaling, RSPO1 may regulate EC inflammation and modulate atherosclerosis development." (PMID 41300494, 2025).
cervical cancer (2 papers, 2021 to 2022). A primary or metastatic malignant neoplasm involving the cervix. "It has been found that lncRNA MEF2C-AS1 inhibits cervical cancer by targeting RSPO1 by suppressing miR-592." (PMID 36467881, 2022). "Further, rescue experiment verified that low expression of miR-592 inhibited proliferation, migration and invasion of cervical cancer cells by regulating RSPO1." (PMID 34169096, 2021).
esophageal cancer (2 papers, 2019 to 2024). A primary or metastatic malignant neoplasm involving the esophagus. "The aim of this study was to establish a robust RSPO1-related signature specific to esophageal cancer (ESCA)." (PMID 38962149, 2024).
granulosa cell tumor (2 papers, 2021 to 2022). A slow-growing, malignant tumor, characterize by the presence of granulosa-like cells and Call-Exner bodies, that is almost always found in the ovary. "Overexpression of Rspo1 in the mouse ovary has been associated with the development of granulosa cell tumors." (PMID 36430923, 2022).
intestinal tumor (2 papers, 2019 to 2024). "For example, gene fusions involving R-spondin 1 occurring in 10% of intestinal tumor are mutually exclusive with active Wnt signaling caused by APC or CTNNB1 mutations." (PMID 31905853, 2019). "Remarkably, the addition of RSPO1 increased the size of Apcmin mouse intestinal tumor organoids in agreement with a previous report although it did not significantly affect the frequency of organoids detected." (PMID 38260423, 2024). "The discrepancy of R-spondin 1 dependence between tumorigenicity induced by the current method and previous GEMM relied on Apc depletion or CTNNB1 activation is supported by the mutual exclusion of R-spondin fusion and Apc or CTNNB1 mutation identified in human intestinal tumors." (PMID 31905853, 2019).
steatosis (2 papers, 2023). Increased lipid within the cytoplasm of cells. "Culturing these mutants in the complete absence of the potential confounding lipid sources (for example, RSPO1-conditioned medium) accordingly did not alter the steatosis phenotypes." (PMID 36823355, 2023).
Alzheimer disease (1 paper, 2023). A progressive, neurodegenerative disease characterized by loss of function and death of nerve cells in several areas of the brain leading to loss of cognitive function such as memory and language. "The RSPO1 increase in humans is considered to be a consequence of the pathology associated with Alzheimer's disease, because spondins have shown protective potential in murine Alzheimer's models." (PMID 36929645, 2023).
cutaneous melanoma (1 paper, 2023). A primary melanoma arising from atypical melanocytes in the skin. "In our study, RSPO1 and RSPO3 were identified as important stroma-to-tumor ligands, each interacting with both the LGR4 and LRP6 receptors in cutaneous melanoma." (PMID 36676129, 2023).
cutaneous squamous cell carcinoma (1 paper, 2022). "We have previously reported that palmoplantar keratoderma (PPK), predisposition to cutaneous squamous cell carcinoma (SCC) development and sex reversal segregate as autosomal recessive trait in patients carrying RSPO1-mutations." (PMID 35854363, 2022).
cyst (1 paper, 2016). A sac-like closed membranous structure that may be empty or contain fluid or amorphous material. "In our study, the cyst formation media contained 4 soluble factors and 2 signal inhibitors such as EGF, HGF, Wnt3a, R-spondin-1, ROCK inhibitor Y-27632, and TGF-β inhibitor A-8301." (PMID 27335264, 2016).
dementia (1 paper, 2023). Loss of intellectual abilities interfering with an individual's social and occupational functions. "In our study, two proteins involved in the Wnt signaling pathway (WNT9A and RSPO1) also showed evidence of differential regulation in dementia." (PMID 37175824, 2023). "Our findings showed that plasma levels of RSPO1 were elevated in subjects with dementia and negatively correlated with the MoCA score." (PMID 37175824, 2023). "Interestingly, this panel of proteins, except RSPO1 and CCL28, were also identified using the machine learning multivariate model (diagnostic Panel B) that discriminated dementia from MCI, with an AUC = 0.87." (PMID 37175824, 2023).
familial Alzheimer disease (1 paper, 2023). A degenerative disease of the brain that causes gradual loss of memory, judgment, and the ability to function socially. "R‐spondin 1 is a positive regulator of canonical WNT/β‐catenin signaling and has been shown to increase in presymptomatic and affected human patients with familial Alzheimer's disease." (PMID 36929645, 2023).
fibrosis (1 paper, 2020). the formation of excess fibrous connective tissue in an organ or tissue in a reparative or reactive process. "Because of the severe phenotypes from RSPO gene knockout studies including embryonic lethality from RSPO3 gene disruption, we generated and used selective monoclonal antibodies against each of three RSPO proteins (RSPO1-3) to test their effects in animal models of fibrosis." (PMID 32160239, 2020).
glioma (1 paper, 2015). A benign or malignant brain and spinal cord tumor that arises from glial cells (astrocytes, oligodendrocytes, ependymal cells). "We found that R-Spondin1 (Rspo1) expression was elevated in high-grade gliomas and was associated with worse overall survival and disease-free survival." (PMID 25865226, 2015). "In this study, we observed that the expression of Rspo1 was significantly associated with poor overall survival and reduced survival of patients with gliomas after treatment with radiotherapy and temozolomide (RT-TMZ)." (PMID 25865226, 2015). "Rspo1 expression was also associated with reduced survival rates in glioma patients after treatment with radiotherapy and temozolomide (RT-TMZ)." (PMID 25865226, 2015). "For the first time, our studies have shown that Rspo1 expression is correlated with the radioresistance of advanced gliomas, which suggests that Rspo1 protects not only normal tissue but also tumor cells from radiation injury." (PMID 25865226, 2015). "In the present study, we demonstrated that a subpopulation of glioma cells express Rspo1, and this subpopulation of gliomas is radioresistant." (PMID 25865226, 2015). "In particular, we showed that radiation treatment triggered a significant increase in the Rspo1 level in patients with gliomas." (PMID 25865226, 2015). "We observed that upregulation of Rspo1 predicted shorter overall survival and disease-free survival in patients with gliomas." (PMID 25865226, 2015). "Compared with normal brain tissue lysate, elevated Rspo1 expression was observed in all six glioma cell lines." (PMID 25865226, 2015). "We next examined the expression of Rspo1 in glioma cell lines using Western blotting assays with anti-Rspo1 antibodies." (PMID 25865226, 2015). "To further investigate the role of Rspo1 in radiation-treated glioma cells, we selected the glioma cell line U87 as our study model." (PMID 25865226, 2015). "Consistent with the results of the immunohistochemical analysis, elevated levels of Rspo1 mRNA were detected in high-grade glioma tissues compared with low-grade gliomas and normal brain tissue samples." (PMID 25865226, 2015). "Immunohistochemical analysis was performed to determine the specific expression of Rspo1 protein in human gliomas." (PMID 25865226, 2015). "In particular, we showed that radiation treatment triggered significant upregulation of Rspo1 in patients with gliomas, and increased cell death was observed upon silencing of Rspo1 via shRNA." (PMID 25865226, 2015). "It would be very interesting to test whether glioma stem cells express Rspo1 and whether Rspo1 inhibition increases the radiation sensitivity of glioma stem cells." (PMID 25865226, 2015). "Notably, the Rspo1 immunostaining was much stronger in high-grade gliomas than in low-grade gliomas." (PMID 25865226, 2015). "Rspo1 silencing by shRNA potentiated glioma cell death upon radiation treatment." (PMID 25865226, 2015). "We also evaluated whether immunoreactivity against Rspo1 was correlated with overall survival in 235 patients with glioma." (PMID 25865226, 2015). "To investigate whether radiation treatment can trigger tumor-specific increases in Rspo1 levels in patients with gliomas, we identified patients for whom tumor samples were available both before and after radiation treatment." (PMID 25865226, 2015). "In this study, we showed that Rspo1 is frequently upregulated in gliomas (43.4%, 102/235), particularly in high-grade glioma (stages III and IV, 52.3%, 68/130), and that a positive association exists between Rspo1 expression and advanced clinicopathological features." (PMID 25865226, 2015). "The mechanism by which Rspo1 regulates glioma cell radioresistance requires further investigation." (PMID 25865226, 2015). "Silencing of Rspo1 in this subpopulation of gliomas could produce good therapeutic effects when combined with radiation therapy." (PMID 25865226, 2015).
glioma (continued). "Importantly, Rspo1 was dramatically upregulated after radiation treatment in patients with glioma." (PMID 25865226, 2015).
intrahepatic cholangiocarcinoma (1 paper, 2015). A carcinoma that arises from the intrahepatic bile duct epithelium in any site of the intrahepatic biliary tree. "In addition, a novel Rspo1-Wnt-Vegfc-Vegfr3 signaling pathway has been defined to play an essential role in developmental angiogenesis, and an aberrant expression of VEGFC was recently found to be associated with lymph node metastasis in intrahepatic cholangiocarcinoma (IHCC)." (PMID 26060426, 2015).
invasive ductal carcinoma of the (1 paper, 2013). "Using 100 cases of invasive ductal carcinoma tissue, we screened expressions of RSPO1, WNT1, WT1, P16, and SDC1 using immunohistochemistry." (PMID 24373193, 2013). "To better understand the mechanisms of the SDC1 expression in invasive ductal carcinoma, we studied the correlations between SDC1 expression and related gene expressions (RSPO1, WNT1, WT1, and P16)." (PMID 24373193, 2013).
malignant glioma (1 paper, 2015). A grade III or grade IV glioma arising from the central nervous system. "Our results thus underscore an important role for Rspo1 in the radioresistance of malignant gliomas and provide novel evidence of the potential therapeutic utility of Rspo1 for the treatment of malignant gliomas." (PMID 25865226, 2015).
nail dystrophies (1 paper, 2022). "RSPO1-mutated XX-sex reversed AN patient suffers from PPK since birth, and also manifests sclerodactyly of the hands, nail dystrophies, and a strong predisposition to develop in adulthood malignant SCCs in PPK skin." (PMID 35854363, 2022).
osteoarthritis (1 paper, 2022). A noninflammatory degenerative joint disease occurring chiefly in older persons, characterized by degeneration of the articular cartilage, hypertrophy of bone at the margins and changes in the synovial membrane. "In addition, enhanced expression of LGR5 and RSPO2 was detected in chondrocytic differentiation of human chondrocytes in advanced stage of osteoarthritis, while elevated expression of LGR6 and RSPO1 was observed in osteogenic differentiation of SaOS‐2 cells." (PMID 35668632, 2022).
Palmoplantar hyperkeratosis (1 paper, 2008). Abnormal thickening of the skin localized to the palm of the hand and the sole of the foot. "Intriguingly, both RSPO1, FOXL2 and PIS mutations are also associated with failure of epithelium differentiation at different specific position, palmoplantar hyperkeratosis in RSPO1-/- patients, eyelids malformation in FOXL2+/- patients and hornless in PIS-/- goats." (PMID 18384673, 2008).
renal hypoplasia (1 paper, 2023). Renal hypoplasia is a developmental anomaly in which one or both kidneys (unilateral or bilateral renal hypoplasia, respectively) have a deficit in the number of nephrons and may be small. "Kidney-specific deletion of Rspo3 results in a mild reduction of renal progenitor cells, whereas joint deletion of Rspo1 and Rspo3 resulted in severe renal hypoplasia." (PMID 37580336, 2023).
skin carcinoma (1 paper, 2016). "RSPO1 appears to function as a tumor suppressor in skin carcinoma, suggesting that the function of Wnt/RSPO signaling in cancer could be context-dependent." (PMID 27338477, 2016).
testicular disorder (1 paper, 2022). A non-neoplastic or neoplastic disorder affecting the testis. "Previous research has shown that RSPO1 mutation causes 46, XX testicular disorder of sex development, and that is contrary to relatively normal spermatogenesis in CAVD patients." (PMID 36437957, 2022).
tetra-amelia syndrome (1 paper, 2022). "Human genetic studies revealed that RSPO1 is critical for ovarian development, and RSPO2 mutation leads to tetra-amelia syndrome including lung aplasia and a lack of limbs, while RSPO4 is necessary for human nail formation." (PMID 34847079, 2022).
tumor (67 papers, 2009 to 2025). "BI-905677 exhibited antitumor activity in preclinical trials, such as the ring finger protein 43 (RNF43) mutation tumor model and R-spondin 1 (RSPO) fusion tumor model." (PMID 40176913, 2025). "Since Apc loss constitutively activates the Wnt pathway, Rspo1 was dispensable for the culture of Apc-deficient tumor organoids." (PMID 27143627, 2016). "Single-agent treatment (Ad-Rspo1 shRNA1 or radiation) according to this administration protocol was associated with detectable but weak tumor growth inhibition, which was resolved during the treatment." (PMID 25865226, 2015). "WT1 was associated with tumor grade (P = 0.025) and RSPO1 was associated with progesterone receptor expression (P = 0.019)." (PMID 24373193, 2013). "Indeed, the enhanced glial progenitor-like profiles including Rspo1, Zfp423, and Msx1 were significantly reduced, whereas Otx2 mRNA levels remained unaltered in Sox2-deficient tumor cells." (PMID 40128799, 2025). "GSEA and KEGG analyses showed that RSPO1 was associated with tumor and immune pathways." (PMID 38962149, 2024). "GSEA and KEGG showed that RSPO1 was associated with tumor and immune pathways." (PMID 38962149, 2024). "However, co-treatment of radiation and Ad-Rspo1 shRNA1 was associated with stronger and prolonged tumor growth inhibition." (PMID 25865226, 2015). "However, the mechanism underlying the role of R-spondin 1 (RSPO1) in tumor immunology remains unclear." (PMID 38962149, 2024). "In TIMER database analysis, 14 types of tumor tissues (including ESCA tissues) showed decreased RSPO1 mRNA levels compared with those of normal tissues." (PMID 38962149, 2024). "As with most tumor organoids, the addition of common growth factors such as wnt-3a, noggin, R-spondin-1 to MPMO culture is beneficial to its development." (PMID 38200517, 2024). "Second, the mechanism of RSPO1-mediated tumor immunity and the prognostic significance of immunological signals required further investigation." (PMID 38962149, 2024). "In summary, our investigation underscores the pivotal role of RSPO1 in orchestrating tumor immunity and proposes RSPO1 as a prospective target for immunotherapeutic interventions in ESCA." (PMID 38962149, 2024). "To identify a more precise immunotherapeutic target for ESCA, we investigated the link between RSPO1 and tumor-infiltrating lymphocyte surface markers." (PMID 38962149, 2024). "In conclusion, our findings strongly suggest that RSPO1 plays a pivotal role in the tumor immune microenvironment." (PMID 38962149, 2024). "In a xenograft nude mouse model, combining radiation and silencing of Rspo1 potentiated tumor growth inhibition." (PMID 25865226, 2015). "As a result, we showed that the combination of radiation with silencing of Rspo1 potentiated the inhibition of tumor growth in a xenograft nude mouse model." (PMID 25865226, 2015). "As a result, we showed that the combination of radiotherapy with Rspo1 silencing potentiated tumor growth inhibition in a xenograft nude mouse model." (PMID 25865226, 2015). "Together, these findings suggest that RSPO1 plays important roles in tumor immunity." (PMID 38962149, 2024). "Besides, the data from GEPIA website showed that the expression level of RSPO1 was significantly decreased in tumor tissues, compared with normal tissue." (PMID 34169096, 2021). "This additional layer of ERα regulation by Rspo1 could be hijacked during tumor initiation or progression." (PMID 32749219, 2020). "Also, Lgr5 is known to exhibit tumor-suppressive activity in the colon, which results from suppression of tumor growth and metastasis regulated by RSPO1/Lgr5-mediated activation of TGFβ signaling." (PMID 31358061, 2019). "The tumor organoids derived from Apc-deficient tumors can be stably maintained in culture medium without Rspo1 and form cystic organoid structures, because Apc loss constitutively activates the Wnt signaling pathway in tumor cells." (PMID 27143627, 2016).